FGL1 (fibrinogen like 1)
Diseases named in the same sentence as FGL1 in open-access papers (continued):
Sharing a sentence is not in itself a finding about the gene and the disease.
tumor (continued). "Recent study has demonstrated that fibrinogen-like protein 1 (FGL1) is a new major ligand for LAG-3, and blocking the FGL1-LAG-3 pathway can stimulate tumor immunity and inhibit tumor growth." (PMID 32762721, 2020). "Even though our data support a functional role for CD4+ T cells in effective anti-parasite immunity, the fibrinogen-like protein 1 (FGL-1) appears as a major ligand of LAG-3 that works independently of MHC-II, and inhibits T cell-mediated anti-tumor immunity." (PMID 33519801, 2020). "Recently, the fibrinogen like protein 1 (FGL-1) that is naturally expressed by liver cells and overexpressed by some tumor cells, was also characterized as a new ligand for LAG-3 which can potently prevent T cell activation upon binding." (PMID 33519801, 2020). "Through their research on cancer, these researchers found that FGL1 is the main ligand of the immunosuppressive receptor LAG-3 and participates in the immune escape mechanism of tumor cells." (PMID 31921022, 2019). "The ligands for LAG-3 in the tumor microenvironment are MHC II (major histocompatibility complex class II), galactose-lectin-3 (Galectin-3), hepatic sinusoidal endothelial cell lectin (LSECtin), fibrinogen-like protein 1 (FGL1), and α-synuclein." (PMID 40362333, 2025). "FGL1 exhibits high affinity for LAG-3, and their interaction facilitates tumor immune escape." (PMID 40356928, 2025). "This bidirectional regulation of FGL1 by ETV4 suggests a complex relationship between these two proteins, which may vary depending on the tumor type and cellular context." (PMID 40469297, 2025). "Initial studies demonstrated its ability to impede HCC progression, while recent findings have identified FGL1 as a functional ligand of lymphocyte activation gene 3 (LAG-3), thereby promoting HCC progression through modulation of the tumor microenvironment (TME)." (PMID 38816776, 2024). "Tumor-infiltrating hepatic CD8+ T and NK cells upregulated the expression of lymphocyte activation gene-3 (LAG-3) and exhibited stronger antitumor activities after anti-FGL1 treatment." (PMID 38973608, 2024). "FGL1 is positively correlated with Treg and MDSC populations, as determined by analysis of the TIMER database, suggesting the regulatory effect of FGL1/LAG-3 signaling on immunosuppressive cells in the tumor microenvironment." (PMID 38973608, 2024). "Although the expression of the other four ligands (HMGB1, CEACAM-1, LSECtin, and FGL-1) did not considerably affect the frequency of tumor-infiltrating CD8+ T cells, the negative relationship was consistent for the four important ligands." (PMID 38390332, 2024). "Similar to FGL1, FGL2 plays opposite roles in different tumor types." (PMID 38903931, 2024). "FGL-1 is another ligand for LAG-3, expressed in hepatocytes, tumor cells, and some immune cells." (PMID 39660130, 2024). "Other ligands, including fibrinogen-like protein 1 (FGL1), galectin-3 (Gal-3), and liver sinusoidal endothelial cell lectin (LSECtin), have been identified to bind with LAG-3, thereby suppressing CD8-mediated anti-tumor responses." (PMID 38785789, 2024). "Previous studies on the abnormal expression of FGL1 in tumor tissues have suggested that the IL6/Stat3 signaling pathway, YY1, HNF1a, and other factors may affect the transcription of FGL1." (PMID 39085849, 2024). "Furthermore, anti-FGL1 mAb treatment was performed in Cd8–/– mice and Nfil3–/– mice challenged with MC38 tumor cells." (PMID 38973608, 2024). "Using an established CRC liver metastasis model of MC38 tumor cells, anti-FGL1 mAb treatment slightly (but not significantly) increased the frequency of CD8+ T cells and promoted the absolute number of CD8+ T cells in the liver on day 21 after MC38 challenge." (PMID 38973608, 2024). "Furthermore, quantification of IHC staining of tumor tissues demonstrated that FGL1 protein levels were positively correlated with SIRT2 expression levels, while the levels of relative acetyl-K98 FGL1 were negatively correlated with SIRT2 expression levels." (PMID 37115693, 2023).
tumor (continued). "The results show that FGL1 protein expression was distinctly elevated in liver metastatic tumor cells, but not elevated in hepatocytes from metastatic livers, which secrete FGL1 under normal physiological conditions." (PMID 37872170, 2023). "The results indicated that FGL1 did not directly affect the proliferation of tumor cells but possibly affected CD8+ TRM cells via FGL1-LAG-3 binding." (PMID 36993960, 2023). "To validate whether aspirin-induced FGL1 degradation benefits HCC immunotherapy in vivo, we selected PD-L1 blockade with aspirin for the combination therapy in Hepa 1-6 and H22 tumor models." (PMID 37115693, 2023). "Furthermore, depletion of B and T cells mitigated the antitumor effects of FGL1 and LAG-3 inhibition, suggesting that FGL1 contributes to tumor growth by inhibiting antitumor immunity." (PMID 37115694, 2023). "To determine whether SIRT2 and relative acetyl-K98 FGL1 levels correlated with HCC progression, we analyzed the clinical data on tumor stages and IHC staining results." (PMID 37115693, 2023). "Since FGL1 is a newly identified immune checkpoint ligand and inhibition of SIRT2 by AGK2 could decrease FGL1 levels in HCC cells, we then determined whether pretreatment of tumor cells with AGK2 would affect T cell activity." (PMID 37115693, 2023). "Among patients in early TNM stage, 18 patients (24.32%) were FGL1 positive, 56 (75.68%) were FGL1 negative; In patients with advanced-stage tumor, 22 (62.86%) were FGL1 positive patients (62.86%), and 13 were FGL1 negative (37.14%)." (PMID 35273912, 2022). "Intriguingly, when FGL1/LAG3 and PD-1/PD-L1 axes were simultaneously inhibited, the therapeutic effect was significantly improved, evidenced by a longer lifespan and reduced tumor burden in mice." (PMID 34975333, 2022). "In particular, various reports demonstrated that MYH9 is involved in tumor proliferation, migration, and metastasis, in this study, YY1 and MYH9 may be the upstream and downstream molecule of FGL1, respectively." (PMID 36268014, 2022). "Moreover, western blot was used to further compare the expression levels of FGL1 in HCC cell lines, HCC tissues, peri-tumor tissues and normal liver tissues." (PMID 35776395, 2022). "We believe that even in these patients with no response to PD-1/PD-L1 inhibitors, FGL1/LAG-3 is involved in the suppression of anti-tumor immunity and results in therapeutic effect." (PMID 35273912, 2022). "Further, the FGL1 expression profile for 11 pairs of fresh tissues collected from HCC patients revealed that the expression was the lowest in HCC tissues, compared to normal and peri-tumor tissues." (PMID 35776395, 2022). "Furthermore, FGL1 expression in primary HCC tissues was also found to be lower than normal tissues and peri-tumor tissues." (PMID 35776395, 2022). "Hence, the relationship between FGL1 and EMT progression in tumor cells still needs to be further investigated." (PMID 34526102, 2021). "Upon engagement with MHC class II molecules, or its newly described ligand, fibrinogen-like protein 1 (FGL1), LAG-3 negatively regulates T and NK cells, thereby promoting tumor escape likely by promoting exhaustion in combination with other checkpoints such as PD1." (PMID 33925565, 2021). "A recent study demonstrated that agents targeting the FGL1/LAG-3 pathway could stimulate tumor immunity and inhibit tumor growth." (PMID 33633363, 2021). "further demonstrated that FGL1 can inhibit the activity and growth effect of T cells and disrupt the interaction between FGL1 and LAG-3 through genetic ablation or monoclonal antibody blockage to significantly improve T cell responses and promote anti-tumor immunity." (PMID 34975855, 2021). "In addition, a correlation between FGL1 and the EMT process has also been reported in a pulmonary fibrosis model, which is distinct from tumor models." (PMID 34526102, 2021). "FGL1 silencing accelerates CD8+ and CD4+ T cell immunity against tumor growth." (PMID 33867830, 2021).
tumor (continued). "The data showed that the FGL1 protein was expressed in local pan-keratin-positive tumor cells but the stromal compartment exhibited almost no expression." (PMID 34526102, 2021). "Chromosome 8p is already known to contain many tumor suppressors, such as DLC1 and FGL1." (PMID 27391266, 2016). "Importantly, FGL1 downregulation significantly inhibited the expression of EMT-related molecules such as TGF-β, Slug, and Snail, while increasing E-cadherin expression, which is important for tumor metastasis (P < 0.05)." (PMID 41024301, 2025). "Additionally, the frequency of nTregs was increased and the frequency of pDCs was decreased in the liver with MC38 tumor cells; however, anti-FGL1 mAb treatment did not alter the frequencies or numbers of Tregs and pDCs in the liver." (PMID 38973608, 2024). "No direct effects of FGL1 on tumor cell proliferation or migration were observed in vitro." (PMID 38973608, 2024). "In addition to galectin-3 and LSECtin, fibrinogen-like protein 1 (FGL1) is another important ligand for LAG-3 as a soluble protein that is released by the liver under normal conditions, and FGL1 is highly expressed in a few tumor tissues." (PMID 37055849, 2023). "While the authors provide mechanistic support for this result, one potential weakness was the lack of assessment for FGL1 acetylation in the in vivo experiments, or in assays of T cell–mediated tumor killing, raising the possibility that antitumor immunity results from some unmeasured effect." (PMID 37115694, 2023). "In addition, patients with FGL1 positive circulating tumor cells had worse postoperative survival than FGL1 negative patients (p=0.0297)." (PMID 35273912, 2022). "It will be interesting to investigate whether dual treatment of anti-LAG-3 antibodies which strongly block both MHC-II and FGL1 improves anti-tumour immunity compared to monotherapy, or if there are no benefits from inhibiting both ligands." (PMID 35265944, 2022). "Patients were divided into two groups according to whether circulating tumor cells express FGL1, 40 and 69 cases for positive and negative group, respectively." (PMID 35273912, 2022). "In addition, in animal experiments, more than 30% of MC38 tumor-bearing mice were found to have no tumor formation within 150 days of treatment with anti-FGL1/LAG3 as a monotherapy or in combination with anti-PD-1/PD-L1 therapy." (PMID 34526102, 2021). "On the other hand, in the mechanism of FGL1-mediated gefitinib resistance, FGL1 was found to regulate apoptosis through the PARP1/caspase-3 pathway, which also confirmed that FGL1 is pertinent to the sensitivity of tumor cells to targeted EGFR-tyrosine kinase inhibitors (TKIs)." (PMID 34526102, 2021). "Both anti-FGL1 and anti-LAG3 could promote anti-tumor T cell immunity." (PMID 33344447, 2020). "Moreover, together with the co-expression of PD-1, the anti-tumor immunity of CD8+ T cells could be abolished through the interaction with LAG-3’s other ligands i.e., LSECtin, FGL-1, and Gal-3 found in the TME." (PMID 33374804, 2020). "FGL1-LAG-3 interaction is another tumor immune escape pathway independent of B7-H1-PD-1 pathway." (PMID 33344447, 2020). "However, the expression levels of its receptor LAG-3 were significantly increased on tumor-infiltrating hepatic CD8+ T and NK cells from MC38 tumor–bearing mice compared with control mice, suggesting that there may be an FGL1/LAG-3 interaction in the liver tumor microenvironment." (PMID 38973608, 2024). "Conversely, tumor cells exhibited positive staining for the three primary LAG-3 ligands (HLA-DR, FGL-1, and galectin-3), while being negative for PD-L1." (PMID 38336861, 2024). "Although there are currently no mAbs targeting FGL1, many mAbs targeting LAG-3 are undergoing clinical trials, including relatlimab (first LAG-3 mAb), and show good potential in tumor immunotherapy." (PMID 37872170, 2023).
tumor (continued). "Using mIF and image analysis approaches, we evaluated the location and abundance of LAG-3, FGL1, PD-L1, and CD8+ T cells in 143 pairs of HCC and matched non-tumor liver tissues." (PMID 32762721, 2020).
cancer (74 papers, 2013 to 2025). A tumor composed of atypical neoplastic, often pleomorphic cells that invade other tissues. "Human cancer cells produce high levels of FGL1, and increased peripheral levels of FGL1 in cancer patients have been associated with a poor prognosis and resistance to anti-PD-1/B7-H1 therapy." (PMID 39057061, 2024). "FGL1 is upregulated in several human cancers and it is associated with impaired outcome and blocking of FGL1-LAG-3 interaction enhances T cell response and improves antitumor immunity." (PMID 33747915, 2021). "Here, we developed a double nanobody sandwich ELISA for human FGL1 detection as a cancer diagnostic." (PMID 33633363, 2021). "High expression of FGL1 in cancer tissues is closely associated with distal metastasis and fatal outcome in ccRCC patients." (PMID 34956878, 2021). "FGL1 is upregulated in most human cancers and is associated with poor prognosis and treatment outcomes." (PMID 32461587, 2020). "Univariate and multivariable Cox proportional hazard regression analyses further showed that, high FGL1 expression in cancer tissues is an independent risk factor for ccRCC patients with poor prognosis, indicating that FGL1 may be an oncogene of ccRCC." (PMID 34956878, 2021). "In addition, high plasma FGL1 expression is associated with poor response to immunotherapy, suggesting FGL1 as a potential biomarker for predicting the outcome of cancer immunotherapy." (PMID 34069373, 2021). "In addition, FGL1 is highly presented in human cancer cells, and elevated FGL1 in the plasma of cancer patients is associated with a poor prognosis and resistance to anti-PD-1/B7-H1 therapy." (PMID 32411209, 2020). "Aberrant expression of LAG3, which is interdependent with its ligand FGL-1 and inhibits T-cell function, has been reported to be negatively associated with clinical prognosis in a variety of cancers, including solid tumors and some cancers of hematological origin." (PMID 40411616, 2025). "Time resolved FRET tested small molecule inhibition of LAG-3 on T cells in relation to FGL1 on human cancers while nanosensors identified specific exosomes to try to diagnose cancer earlier." (PMID 40625731, 2025). "IHC confirmed the high expression of FGL1 in cancer tissues, whereas ChIP-qPCR and dual-luciferase reporter gene assays identified ETS1 as a transcription factor that mediates its high expression." (PMID 41024301, 2025). "Single-cell sequencing transcription factor analysis was performed to elucidate the reasons for the high FGL1 expression in cancer tissues." (PMID 41024301, 2025). "FGL1 has also been described as a mediator of immune evasion in certain cancers but this function has since been questioned." (PMID 40832769, 2025). "FGL1 staining and H-score quantification indicated that FGL1 expression was higher in cancer tissues than in paracancerous tissues (P < 0.0001)." (PMID 41024301, 2025). "These biomimetic nanoparticles enhance cargo endosomal escape, with metformin suppressing PD-L1 through AMPK upregulation, and siRNA reducing FGL1 expression to boost anti-cancer immunity through T cell induction." (PMID 38566199, 2024). "Our findings demonstrated significantly higher expression of FGL1 in cancer tissues compared to adjacent normal tissues." (PMID 39085849, 2024). "Of note, pH-sensitive biomimetic nanocarriers, crafted from PLGA and coated with membranes from macrophages and cancer cells, can deliver FGL1-siRNA and metformin for cancer immunotherapy." (PMID 38566199, 2024). "The results were consistent with those from database analysis, showing that FGL1 expression was significantly higher in cancer tissues compared to adjacent normal tissues." (PMID 39085849, 2024). "The interaction of LAG-3 with its ligands, such as MHC-II, Galectin-3, LSECtin, and FGL-1, highlights its potential as a therapeutic target and prognostic biomarker for cancer." (PMID 39660130, 2024).
cancer (continued). "To validate our findings from public database analysis, we used NSCLC tissue microarrays and detected the expression of FGL1 protein in cancer tissues and adjacent normal tissues." (PMID 39085849, 2024). "It was reported that elevated fibrinogen-like protein 1 (FGL1), a major LAG-3 functional ligand independent from MHC-II, is associated with a poor prognosis and resistance to anti-PD-1/B7-H1 therapy in cancer patients." (PMID 38724599, 2024). "Here, we identify that fibrinogen-like protein 1 (FGL1), secreted from cancer cells and hepatocytes, facilitates the progression of CRC in an intraportal injection model by reducing the infiltration of T cells." (PMID 37872170, 2023). "For instance, recent studies have shown that CD24 promotes immune evasion by interacting with Siglec-10 in tumors, and FGL1-LAG-3 interaction mediates T cell suppression in various cancers." (PMID 37566630, 2023). "Since the establishment of FGL1 as a high-affinity ligand of LAG-3 in 2019, the pharmaceutical industry has shown great enthusiasm in developing anti-FGL1 immunotherapy for cancer patients, especially NSCLC patients." (PMID 38098892, 2023). "The immune-modulatory functions of FGL2 relative to FGL1 are more extensively described, in general and in the context of cancer." (PMID 37115694, 2023). "Consistently, the plasma FGL1 levels were significantly higher in cancer patients than in healthy donors, and the levels were also significantly increased in metastatic CRC or GC patients compared with patients without liver metastases." (PMID 37872170, 2023). "FGL1 is highly produced by human cancer cells and binding of LAG-3 with FGL1 contributes to poor responses/resistance to anti-PD-1/anti-PD-L1 immunotherapies." (PMID 37569880, 2023). "IB analysis showed that treatment with benzethonium chloride decreased the protein expression of FGL1 in cancer cells." (PMID 37872170, 2023). "Under normal circumstances, the expression of FGL-1 is low in hepatocytes, and its expression markedly increases when cancers occur." (PMID 35494015, 2022). "Previous studies have reported the downregulation of FGL1 in HCC, and a strong correlation between FGL1 expression and the differentiation status of malignant tumors." (PMID 35776395, 2022). "Further, a search of existing OMICS data using the UALCAN website suggested that FGL1 expression was significantly related to individual cancer stages (P < 0.05)." (PMID 35776395, 2022). "Blockade of the FGL1/LAG3 pathway has been exploited by many a researcher as an immunotherapeutic route for cancers." (PMID 34975333, 2022). "The expression profile of FGL1 in multiple malignant tumors was bioinformatically determined using the GEPIA 2 webserver." (PMID 35776395, 2022). "Recent studies have increasingly focused on FGL1 for its possible role in the prognosis and treatment of various malignant tumors." (PMID 35776395, 2022). "Studies have shown that FGL1 is abundantly secreted in multiple cancers, including lung cancer, prostate cancer, melanoma, and colorectal cancer." (PMID 35494015, 2022). "Despite the potential of FGL1 as a new cancer biomarker and therapeutic target, there are few related studies and much of what has been reported are superficial and lack depth and particularity." (PMID 34975333, 2022). "According to these findings, elevated FGL1 expression in the plasma of cancer patients is related to poor prognosis." (PMID 36011329, 2022). "The immunosuppressive effects of FGL1 or FGL2 makes them a good target in a promising immune checkpoint blockade strategy during treatment of cancer, especially because they are upregulated in various solid tumors." (PMID 35885017, 2022). "It suggested that FGL1 expression was related to late-stage carcinoma and distant metastasis, which contributed to the poor prognosis of patients." (PMID 35273912, 2022).